APP (amyloid beta precursor protein)
Diseases named in the same sentence as APP in open-access papers (continued):
Sharing a sentence is not in itself a finding about the gene and the disease.
cognitive decline (continued). "Notably, the early onset of cognitive decline aligns with the known pathogenic potential of APP variants; however, the slow progression over two decades is certainly atypical in the context of intermediate ACNCP and CAA." (PMID 41551043, 2025). "Aβ contributes to mitochondrial fragmentation and synaptic loss, while dysfunctional mitochondria may exacerbate cognitive decline by increasing the accumulation of Aβ derived from APP." (PMID 39705440, 2024). "In addition to tauopathy, cognitive decline in AD-related dementia is associated with neuritic β-amyloid (Aβ) plaques resulting from the interplay between APP and APOE55." (PMID 38849415, 2024). "Interestingly, an APP missense mutation (A673T) has been described that decreases APP cleavage by β-secretase and lowers the risk of AD and cognitive decline further supporting the critical role of APP-cleavage in AD pathophysiology." (PMID 37940777, 2024). "Evidence shows that the APOEε4 allele influences autosomal dominant EOAD, because in patients with pathogenic variants of APP, the APOEε4 allele is associated with faster cognitive decline, whereas in carriers of pathogenic variants of PSEN1, an inverse effect is observed." (PMID 37958671, 2023). "APP is hydrolyzed to Aβ1-40 and Aβ1-42 by γ-secretase, of which Aβ1-42 is the main component in the formation of senile plaques and causes neuronal death and cognitive decline." (PMID 37630692, 2023). "Similarly, knock-out of CX3CR1 in APP mice resulted in exacerbated tau pathology, cognitive decline, and memory loss, paralleled by increased levels of the pro-inflammatory cytokine IL-6." (PMID 35821178, 2022). "Having three-copies of APP in DS is necessary for the development of AD-associated cognitive decline, but whether this is due to increased Aβ production, loss of cholinergic neurons, another mechanism, or these working in synergy, is unclear." (PMID 35747206, 2022). "Furthermore, this mutation has a synergistic effect with enhanced APP production to exacerbate cognitive decline in the tg-AD mouse model." (PMID 36418293, 2022). "AβOs were not able to induce memory deficit in mutant mice with loss of APP, suggesting that either APP is a key component of cognitive decline or that Aβ aggregates affect cognition by a yet unknown mechanism." (PMID 35885050, 2022). "Alternatively, PKCα may act downstream of APP, accounting for why the variant accelerates APP-induced cognitive decline." (PMID 36418293, 2022). "Hardy and Allsop, 1991, proposed the most accepted hypothesis that amyloid-β precursor protein (APP) misprocessing and deposition of pathogenic Aβ fragments is the primary driver of the progressive neuron and synapse loss underlying cognitive decline." (PMID 34063708, 2021). "Even if the associations between early stages of AD, progressive cognitive decline, reductions of APP ratio or alterations of secretases activity were demonstrated it is still uncertain if these elements can serve either as reliable biomarkers for preclinical stage of AD or as therapeutic targets." (PMID 34440494, 2021). "BaP-induced neuronal loss in 7-month APP/PS1 mice promoted cognitive decline seen in APP/PS1 mice." (PMID 32867800, 2020). "Our finding that inhibiting Akt-mediated HTT phosphorylation reduces APP presynaptic levels in APPPS1 mice suggests that increased Akt activity might contribute to higher presynaptic APP levels in AD brains, leading to synapse loss and cognitive decline." (PMID 32452382, 2020). "Through modest but significant downregulation of APP gene expression, fingolimod could protect against brain atrophy and cognitive decline associated with amyloid-β accumulation in chronic HIV infection." (PMID 28913617, 2017). "The A673T mutation in APP (alternatively called A2T mutation in Aβ) was shown to reduce amyloidogenic Aβ production and aggregation, providing protection against age-associated cognitive decline." (PMID 28197669, 2017).
cognitive decline (continued). "Particularly, the oxygen responsive HIF-1α subunit may significantly contribute to the cognitive decline by influencing some mechanisms associated with APP amyloidogenic metabolism." (PMID 27294139, 2016). "The recent discovery of a coding mutation on the APP gene (A673T) which provides significant protection against cognitive decline in both AD patients as well as normal elderly individuals is strong proof of the principle evidence that reducing Aβ levels is an effective therapeutic approach for AD." (PMID 23531149, 2013). "For instance, it has been shown that reestablishing gamma oscillation by overexpression of the Nav1.1 channel reduces the aberrant epileptiform activity and the cognitive decline in the transgenic mouse expressing the APP with the Swedish and Indiana mutations." (PMID 26316994, 2013). "For example, enhanced amyloid precursor protein (APP) expression and Aβ peptide level, or other Alzheimer protein expression, have been demonstrated in the ischemic brain, which caused the development of neuronal degeneration and ultimately cognitive decline of Alzheimer type." (PMID 32264971, 2020). "Furthermore, APP mutation is the primary contributor to the increased FC in the caudate-rMFG tract, which might be due to a compensatory mechanism that prevents cognitive decline, or reflect the early pathological changes." (PMID 31937364, 2020). "Thus alterations of oxygen responsive HIF-1α subunit in the central nervous system may contribute to the cognitive decline, especially influencing mechanisms associated to amyloid precursor protein (APP) amyloidogenic metabolism." (PMID 24478626, 2014). "For instance, female APP/PSEN1 transgenic mice exhibit more rapid cognitive decline than males, reflecting a higher prevalence of AD in females, making them useful for studying sex differences." (PMID 40420360, 2025). "To elucidate the pathophysiological role of Tn‐R in Aβ metabolism and cognitive decline, we performed region‐specific Tn‐R knockdown via lentiviral‐mediated shRNA delivery in the perforant pathway of 4‐month‐old APP/PS1 mice." (PMID 40891036, 2025). "In NPC1 models of NP disease, cholesterol and sphingolipids accumulate in lysosomes and the trans-Golgi network, disrupting vesicle trafficking and triggering APP misprocessing, tau abnormalities, and cognitive decline." (PMID 41278977, 2025). "A recent study also demonstrated that exogenous OCN administration reduced brain Aβ burden and cognitive decline in amyloid precursor protein (APP)/PS1 mice." (PMID 40547941, 2025). "Mn exposure alters non-amyloidogenic APP processing, impairing cognition and synaptic function, linking APP dysregulation to cognitive decline." (PMID 40278152, 2025). "In AD, APP processing generates Aβ, leading to plaque formation, neuronal damage, and inflammation, ultimately contributing to cognitive decline." (PMID 40018519, 2025). "Namely, inhibition of polo-like kinase 2 prevented cognitive decline in a sex-dependent manner in male APP/PS1 mice." (PMID 40724648, 2025). "AD, the most common cause of dementia, is characterized by the buildup of Aβ plaques, amyloid precursor protein (APP) and neurofibrillary tangles of tau protein in the brain, leading to progressive cognitive decline and memory loss." (PMID 41362701, 2025). "Intravenous tail vein administration of OXT in group‐housed 12‐week‐old APP/PS1 mice reduced age‐associated Aβ deposition and neuronal apoptosis, alleviated cognitive decline." (PMID 40635450, 2025). "Microglia-specific knockdown of circDlg1 remarkably ameliorated microglial recruitment and envelopment of amyloid-β (Aβ), mitigated neuroinflammation, and prevented cognitive decline in APP/PS1 mice." (PMID 40093898, 2025). "Compared with age‐matched wild‐type (WT) mice, 6‐ and 9‐month‐old APP/PS1 mice exhibited significant cognitive decline, while all age groups (3‐, 6‐, and 9‐month‐old) of APP/PS1 mice showed significantly reduced CBF." (PMID 41367129, 2025).
cognitive decline (continued). "We reported significant correlations of a subset of these dysfunctions with cognitive decline, AD-related clinical hallmarks and peripheral APP-CTFs accumulation." (PMID 38851733, 2024). "Taken together, these results suggested that SARM1 deletion in CNS alleviated cognitive decline, Aβ deposition and inflammatory infiltration in APP/PS1 mice by downregulation of TNF-α signaling." (PMID 37307837, 2024). "The reported changes of cognitive decline in APP/PS1 mice occurs after 6 months of age and were distinct at 9 months of age." (PMID 39519239, 2024). "RIC enhanced memory‐related protein expression and rescued depressive‐like behavior and cognitive decline in APP/PS1 transgenic rats." (PMID 38379185, 2024). "In line with our results, a recent study showed that administration of a caspase-1 inhibitor to pre-symptomatic APP mutant mice slowed down cognitive decline." (PMID 38230736, 2024). "It has been described that one of the most important features of APP/PS1 mice is cognitive decline in terms of memory and spatial memory." (PMID 36895036, 2023). "Transient depletion of Tregs accelerate cognitive decline, whereas amplification of Tregs including the use of low dose IL-2 improve cognitive outcomes in the same APP/PS1 mice used in this report." (PMID 38111016, 2023). "At 4 months of age, APP‐KI mice begin to show cognitive decline according to the touchscreen‐based behavioral test, which can sensitively detect subtle cognitive changes." (PMID 37822109, 2023). "Further, the reduction of both NCX2 and NCX3 expression seems to be related to cognitive decline in hippocampal CA1 neurons of APP transgenic mice." (PMID 37508434, 2023). "We have shown that hippocampal basal and stimulus-evoked glutamate signaling in APP/PS1 mice becomes hyperactive in a subregion specific manner prior to onset of cognitive decline." (PMID 35821835, 2022). "All these actions contribute to decreasing the production and deposition of Aβ, thus leading to improved cognitive decline in APP/PS1 Tg mice." (PMID 36263378, 2022). "Aberrant processing, accumulation, and deposition of well-studied proteins amyloid-β precursor protein (APP) and Tau contribute to neurodegeneration, neural network malfunction and cognitive decline." (PMID 35733193, 2022). "Aβ is derived from amyloid precursor protein (APP) through the proteolytic cleavage of a family of enzymes (β- and γ-secretase), which leads to memory loss and cognitive decline by the formation of senile plaques." (PMID 35036433, 2022). "An additional study provided further evidence that the enhanced migration of peripheral macrophages to the CNS, induced by glatiramer acetate immunization, curbed Aβ neuropathology and prevented cognitive decline in APP/PS1 mice." (PMID 35954209, 2022). "This compound was shown to prevent cognitive decline and Aβ oligomerization in APP/PS1 mice with higher effectiveness than either substance alone." (PMID 36551821, 2022). "While fast progressing AD models reduce study duration, the slower progression of both pathology and cognitive decline in APP/PS1 mice and other models is ideal for several reasons." (PMID 35821835, 2022). "Based on the pathology and cognitive decline in the APP/PS1 mice compared to their littermate control C57BL/6 mice, 6 months of age corresponds with mild cognitie impairment while 12–15 and 18+ months correspond with mild-AD and AD, respectively." (PMID 35821835, 2022). "For instance, by removing the effect of the 1st PCs of mRNAs (PC1), the variance of APP explained by cognitive decline was reduced by 13.5%." (PMID 35115553, 2022). "Together with the Y-maze data, it appears the antigen vaccination significantly slowed the age-dependent cognitive decline observed in short-term and long-term memory, typically demonstrated in APP/PS1 mice." (PMID 35453459, 2022).
cognitive decline (continued). "Our findings indicate that microinfarct induction in young APP/PS1 mice exacerbates cognitive decline and impairs neurovascular coupling in males, whereas in females those deficits were transient." (PMID 35173711, 2021). "Taken together, these results indicated that gain-of-function of miR-195 rescued cognitive decline of APP/PS1 mice that related to preventing the increase of APP expression but not affecting BACE1 level." (PMID 33981225, 2021). "The data suggested that local hippocampal injection of lentivirus-mediated miR-195 can effectively prevent cognitive decline in APP/PS1 mice at the age of 6 and 7-month old; however, medication time was at least 2 months." (PMID 33981225, 2021). "In previous studies, it has been demonstrated that APP/PS1 mice showed cognitive decline in terms of spatial learning and memory." (PMID 34294142, 2021). "In platelets from AD patients, changes in the ratio between different isoforms of APP were reported, which correlated with a cognitive decline." (PMID 34440494, 2021). "Specifically, Nlrp3(−/−) or Casp1(−/−) mutations in WT and APP/PS1 mice demonstrated reduced hippocampal and cortical inflammation, apoptosis, and Aβ deposition, as well as decreased cognitive decline." (PMID 34211387, 2021). "Based on these observations, we can conclude that long-term administration of indomethacin is beneficial for improving cognitive decline in APP/PS1 Tg mice." (PMID 34360951, 2021). "Our findings advocate for independent but synergistic effects of multifocal microinfarcts and Aβ neuropathology in exacerbating cognitive decline, which was rapid and prolonged in young APP/PS1 males, but mild and transient in females." (PMID 35173711, 2021). "The resulting double mutant mice TG miR-455-3p X hAb-KI predicted to live longer & show reduced cognitive decline and APP and its c-terminal derivative toxicities of mitochondria and synaptic activities." (PMID 34781166, 2021). "Our results reveal the mechanisms by which indomethacin decreases the production and deposition of Aβ, which results in the amelioration of cognitive decline in APP/PS1 Tg mice." (PMID 34360951, 2021). "In the present study, we reported for the first time that gain-of-function of miR-195 in the hippocampus and cortex effectively rescue the cognitive decline in APP/PS1 mice." (PMID 33981225, 2021). "More importantly, treatment with indomethacin and atorvastatin ameliorates the cognitive decline of APP/PS1 Tg mice." (PMID 34360951, 2021). "By inducing A2M expression, the production and aggregation of Aβ were inhibited, which resulted in the amelioration of cognitive decline in APP/PS1 Tg mice." (PMID 34360951, 2021). "A rare variant (A673T) discovered in the well‐known familial AD causal gene, amyloid precursor protein (APP), protects against AD, and related cognitive decline." (PMID 34197020, 2021). "Our data suggest a protective effect of CSF1R gene deletion to prevent cognitive decline in APP cKO mice." (PMID 33402196, 2021). "FMT treatment of APP/PS1 with wildtype mouse feces alleviated cognitive decline, Aβ accumulation, and Tau hyperphosphorylation through reversing alterations in the gut microbiota of APP/PS1 mice." (PMID 33153085, 2020). "Following AAV-mediated delivery of an MCL-1-expressing vector into the hippocampus of these mice, we found that MCL-1 overexpression ameliorates the cognitive decline seen in the APP/PS1 mice and reduces extracellular Aβ plaque in the hippocampus." (PMID 33184293, 2020). "We demonstrate that early administration of EpoD prevented cognitive decline and ameliorated AD-like pathology in the hippocampus of APP/PS1 mice." (PMID 32901091, 2020). "Collectively, chronic BaP exposure induced, accelerated and/or exacerbated AD-like cognitive decline in WT mice and APP/PS1 mice." (PMID 32867800, 2020).
cognitive decline (continued). "FTS•B effectively counteracted cognitive decline by regulating neuroinflammation via NF-κB signaling in APP/PS1 mice, providing preliminary experimental evidence that FTS•B is a promising therapeutic agent in AD treatment." (PMID 33059746, 2020). "In our previous study, we showed that CPP prevented cognitive decline and Aβ accumulation in APP/PS2 mice." (PMID 32075202, 2020). "However, we observed significant negative associations between CSF APP and all measures of clinical severity and cognitive decline within HD mutation carriers, suggesting that APP, and its cleaved product beta-amyloid (Aβ), may be an important avenue to be explored in HD." (PMID 32804976, 2020). "Here, we used an untargeted metabolomics analysis to define system-level alterations following cognitive decline in aged and APP/PS1 (AD) mice." (PMID 32699218, 2020). "We found that compared with the APP/PS1 vehicle mice, WT mice spent less time in locating the platform, indicating that the APP/PS1 vehicle mice exhibited severe cognitive decline in learning." (PMID 31901901, 2020). "Ceftriaxone has been reported to upregulate GLT-1 expression and improve cognitive decline in APP/PS1 mice." (PMID 33132901, 2020). "Cerebroventricular infusion of Ang-II into adult Wistar rats promoted Aβ production and tau pathology, and ARBs and ACEIs protect against cognitive decline and disease pathology in transgenic APP mouse models of AD (reviewed)." (PMID 33380345, 2020). "In the present study, we found that intake of capsaicin, the pungent ingredient in chili peppers, reduced brain Aβ burden and rescued cognitive decline in APP/PS1 mice." (PMID 32661266, 2020). "We found that Klotho overexpression significantly improved cognitive decline, reduced Aβ burden, ameliorated neuronal and synaptic loss, and increased CBF in APP/PS1 mice." (PMID 32964663, 2020). "Taken together, our results suggest that transplantation of APP−/− or APP+/+ mESC-TEPs into AD mice results in clearance of Ab plaques and reversal of cognitive decline, and APP−/− mESC-TEP-treated mice perform better than APP+/+ mESC-TEP-treated mice." (PMID 32849642, 2020). "Reciprocally, the knockdown of the expression of mPGES1 ameliorated the expected cognitive decline by inhibiting the phosphorylation of tau in APP/PS1 Tg mice." (PMID 31143112, 2019). "SR9009 induced the activation of microglia, the increased expression of pro-inflammatory genes, and cognitive decline in 2-month-old APP-KI mice." (PMID 31470863, 2019). "More specifically, PPARγ agonist treatment was shown to improve cognitive decline in Tg2576 APP mice by normalizing dentate granule cell presynaptic function." (PMID 30383537, 2018). "Targeting the cyclic adenosine monophosphate (cAMP)/cAMP-response element binding protein (CREB) pathway, S14 rescued cognitive decline by improving hippocampal neurogenesis in APP/PS1 transgenic mice." (PMID 29458418, 2018). "In AD model mice, spatial learning and memory have been shown to be impaired in nearly all models of Aβ overproduction by transgenic APP expression, and the onset of the cognitive decline occurred close to that of brain amyloid deposition." (PMID 30409172, 2018). "To determine if BFCN lesions in APP/PS1 transgenic mice accelerated cognitive decline, we first tested 6 month old mice for working memory in the Y maze 1 month post-injection of IgG- or p75-saporin into the basal forebrain." (PMID 29520217, 2018). "We discovered that MenSCs reduced Aβ deposition and tau hyperphosphorylation, improved cognitive decline, modulated microglia activation and restored Aβ clearance capacity in APP/PS1 transgenic mice." (PMID 29740283, 2018). "The CPO-Aβ17-21P peptide ameliorates AD-related cognitive decline in APPswe/PSEN1dE9 (APP/PS1) transgenic mice by inhibiting Apolipoprotein E (apoE) and Aβ binding, reducing amyloid deposition, and regulating the inflammatory response." (PMID 30352982, 2018).